ATP8B1 (ATPase phospholipid transporting 8B1)
Diseases named in the same sentence as ATP8B1 in open-access papers (continued):
Sharing a sentence is not in itself a finding about the gene and the disease.
lung fibrosis (3 papers, 2016 to 2022). "The mechanism by which MMP7 may lead to loss of epithelial integrity and eventual lung fibrosis is currently under investigation, and the Atp8b1 mouse model will provide the background on which to explore this mechanism." (PMID 35204783, 2022). "This suggests that Atp8b1 mutant mice may be susceptible to age-induced lung fibrosis mediated in part by MMP13." (PMID 27689529, 2016). "Future studies will explore in greater detail whether Atp8b1 mutant mice are susceptible to age-related lung fibrosis and the molecular mechanisms underlying the disease processes." (PMID 27689529, 2016). "Taken together, these results suggest that Atp8b1 mutant mice may be susceptible to age-related lung fibrosis, a phenotype associated with gene mutation and environmental trigger(s)." (PMID 27689529, 2016). "We have demonstrated here that a specific Atp8b1 gene mutation, coupled with hyperoxic exposure in a murine model, recapitulates a series of pathological events that commences with apoptosis and proliferation of lung epithelial cells and leads to pulmonary fibrosis." (PMID 30636723, 2019). "Abnormal morphology of ciliated cells and club cells in the Atp8b1 mutant mouse and microarray data indicating decreased expression of ciliogenesis genes support a role for ciliogenesis in lung fibrosis in this mouse model." (PMID 35204783, 2022). "As shown here, MMP7 is upregulated at both the transcript and protein levels in the Atp8b1 mutant mouse, which develops pulmonary fibrosis, a phenotype accelerated by hyperoxia." (PMID 35204783, 2022). "Abnormalities in airway epithelia and lung parenchyma are found in Atp8b1 mutant mice, which develop pulmonary fibrosis after hyperoxic insult." (PMID 35204783, 2022). "The similarities between hyperoxia-induced lung fibrosis in Atp8b1 mutant mice and IPF suggest that damage-induced migratory bronchiolar epithelial cells proactively give rise to metaplastic epithelial cells and thereby prompt fibrosis in alveoli." (PMID 30636723, 2019). "Given the emerging links between MMP7 and pulmonary fibrosis in humans, we investigate MMP7 levels in the Atp8b1 mouse lung." (PMID 35204783, 2022). "The most plausible scenario for this observation is that, due to the lack of functional Atp8b1, restoration of normal bronchioalveolar structures is impaired and lung fibrosis perpetuates in Atp8b1G308V/G308V mice." (PMID 30636723, 2019). "The reason for pulmonary fibrosis in the Atp8b1 mouse is not clear." (PMID 35204783, 2022).
lung squamous cell carcinoma (3 papers, 2022 to 2025). "Most recently, ATP8B1 was identified as a prognostic biomarker for prostate cancer and lung squamous cell carcinoma, and that a higher ATP8B1 expression was associated with a better patient prognosis." (PMID 38382846, 2024). "Similarly, ATP8B1 mutations, associated with lipid metabolism, are rarely discussed in LSCC literature but have been proposed as a novel predictive biomarker in lung squamous cell carcinoma." (PMID 41590495, 2025). "Although ATP8B1 plays important roles in cell functions, ATP8B1 has been poorly studied in tumors and its prognostic value in patients with lung squamous cell carcinoma (LUSC) remains unclear." (PMID 35159102, 2022).
cholestasis of pregnancy (2 papers, 2021 to 2022). "Intrahepatic cholestasis of pregnancy (ICP) is also associated with ATP8B1 mutations." (PMID 35783636, 2022).
chronic pancreatitis (2 papers, 2013 to 2022). A chronic inflammatory process causing damage and fibrosis of the pancreatic parenchyma. "We analyzed all 27 ATP8B1 coding exons and adjacent non-coding sequences of 507 chronic pancreatitis patients by direct sequencing." (PMID 24260417, 2013). "In conclusion, our investigation did not reveal an association between heterozygous ATP8B1 variants and hereditary or idiopathic chronic pancreatitis." (PMID 24260417, 2013).
colorectal cancer (2 papers, 2020 to 2022). A primary or metastatic malignant neoplasm that affects the colon or rectum. "However, the function of ATP8B1 in carcinogenesis has been seldom studied, and downregulation of ATP8B1 was reported to be associated with poor prognosis in colorectal cancer without any further explanation of the underlying regulatory mechanism." (PMID 35159102, 2022). "However, the prognostic values of ATP8B1 in colorectal cancer (CRC) patients remain unclear." (PMID 33062669, 2020).
Crohn disease (2 papers, 2020 to 2024). A gastrointestinal disorder characterized by chronic inflammation involving all layers of the intestinal wall, noncaseating granulomas affecting the intestinal wall and regional lymph nodes, and transmural fibrosis. "ATP8B1 expression was investigated in intestinal samples of patients with Crohn’s disease [CD] or ulcerative colitis [UC] as well as in murine models of intestinal inflammation." (PMID 38366839, 2024).
cystic fibrosis (2 papers, 2016 to 2023). Autosomal recessive disorder caused by pathogenic variants in the CFTR gene (cystic fibrosis transmembrane conductance regulator), which encodes a chloride and bicarbonate channel expressed in epithelial cells, and follow the diagnosis criteria. "Loss of ATP8B1 function and downregulation of cystic fibrosis transmembrane conductance regulator (CFTR) in biliary cells can lead to impaired bile acid excretion and may contribute to the development of extrahepatic cystic fibrosis in PFIC1 patients." (PMID 37324459, 2023).
deafness (2 papers, 2009 to 2026). An inherited or acquired condition characterized by the complete loss of the ability to hear from one or both ears. "Together, these findings establish ATP8B1 and TMEM30B as key regulators of membrane lipid asymmetry in sensory hair cells and establish TMEM30B as a novel deafness gene." (PMID 41726979, 2026).
prostate carcinoma (2 papers, 2023 to 2024). A carcinoma that arises from epithelial cells of the prostate gland. "Most recently, ATP8B1 was identified as a prognostic prostate cancer biomarker." (PMID 37686603, 2023).
Wilson disease (2 papers, 2024 to 2025). A very rare inherited multisystemic disease presenting non-specific neurological, hepatic, psychiatric or osseo-muscular manifestations due to excessive copper deposition in the body. "For inherited diseases such as PFIC1, PFIC2, PFIC3, and Wilson’s disease, the coding regions of the ATP8B1, ABCB11, ABCB4, and ATP7B sequences exceed the AAV vector capacity." (PMID 39684224, 2024).
acute lung injury (1 paper, 2019). A condition of lung damage that is characterized by bilateral pulmonary infiltrates (pulmonary edema) rich in neutrophils, and in the absence of clinical heart failure. "With this characteristic, Atp8b1 lowers the elevated cardiolipin level in the airspace which is caused by acute lung injury (ALI)." (PMID 30636723, 2019).
Alzheimer disease (1 paper, 2024). A progressive, neurodegenerative disease characterized by loss of function and death of nerve cells in several areas of the brain leading to loss of cognitive function such as memory and language. "ATP8B1 was associated with resilience to Alzheimer’s Disease (AD) based on the observation that several SNPs within the ATP8B1 enhancer that are enriched in asymptomatic individuals compared to AD patients." (PMID 38382846, 2024).
Ataxia (1 paper, 2018). Ataxia refers to impaired coordination of voluntary muscle movement. "No ataxia phenotypes were observed in Atp8a1 and Atp8b1 KO mice." (PMID 30185775, 2018).
autoimmune disease (1 paper, 2021). A disorder resulting from loss of function or tissue destruction of an organ or multiple organs, arising from humoral or cellular immune responses of the individual to their own tissue constituents. "Eleven proteins (increased: ATP5B, CALML5, COLEC11, FCGBP, PLEK, PLXND1; decreased: APOB, ATP8B1, FAM20C, LOXL3, TIMD4) were significantly altered in bvFTD with autoimmune disease compared to those without autoimmune disease." (PMID 34539672, 2021).
breast carcinoma (1 paper, 2025). "In metastatic tumors, the exclusive presence of mutations in ATP8B1 and FRK in metastatic samples mirrors recent research on colorectal and breast cancers indicating that these genes play a role in tumor dissemination and metastatic colonization." (PMID 41590495, 2025).
colitis (1 paper, 2024). Inflammation of the colon. "Colitis was induced in ATP8B1-deficient mice with dextran sodium sulphate [DSS] and intestinal permeability was investigated." (PMID 38366839, 2024). "ATP8B1-deficient mice were extremely sensitive to DSS-induced colitis, as evidenced by increased intestinal barrier leakage." (PMID 38366839, 2024). "During a DSS-induced intestinal insult [‘second hit’], however, barrier dysfunction was observed even at 3 days post-DSS in Atp8b1-deficient mice, but not in wild-type mice, which progressed to severe epithelial damage and aggravating colitis 6 days after DSS." (PMID 38366839, 2024). "These experiments show that ATP8B1 plays a crucial role in the intestine in DSS-induced colitis." (PMID 38366839, 2024). "In this study, we show that ATP8B1 is highly expressed in epithelial cells of the intestine and is specifically reduced in patients with ulcerative colitis [UC] and in dextran sodium sulphate [DSS]-induced colitis in mice." (PMID 38366839, 2024).
colorectal tumor (1 paper, 2024). "In colorectal tumor tissues, SNP rs34245610 at 18q21.32 was an eQTL for ATP8B1 (p = 0.010)." (PMID 38664626, 2024).
emphysema (1 paper, 2016). "In light of this finding, Atp8b1 mutant mice may be susceptible to develop age-induced emphysema as a result of increased MMP12 levels." (PMID 27689529, 2016).
fibrosis (1 paper, 2019). the formation of excess fibrous connective tissue in an organ or tissue in a reparative or reactive process. "These ambivalent hyperoxia-induced responses that occurred in Atp8b1 deficient lungs were followed at the recovery phase by non-uniform fibrosis, affecting both the peribronchiolar and alveolar areas." (PMID 30636723, 2019).
gallstones (1 paper, 2023). Solid crystalline precipitates in the biliary tract, usually formed in the gallbladder, resulting in the condition of cholelithiasis. "Additionally, the downregulated proteins in gallstone bile showed enrichment in bile acid and bile salt transport (padjusted = 0.004), which included AKR1C1, ABCC2, ABCB11, and ATP8B1." (PMID 38111640, 2023).
Hearing impairment (1 paper, 2025). A decreased magnitude of the sensory perception of sound. "Because IGF‐1 is the key effector of growth hormones and inhibits hair cell apoptosis, we speculate that chronic suppression of IGF‐1 signalling due to reduced blood insulin levels can contribute to growth failure and hearing impairment in PFIC1 patients and Atp8b1 mutant mice." (PMID 40851490, 2025).
hypoglycaemia (1 paper, 2025). "In the present study, we show that ATP8B1 deficiency in mice leads to glucagon resistance and fasting hypoglycaemia and identify that increased PDE4 expression in human and mouse ATP8B1‐deficient hepatocytes mediates this glucagon resistance." (PMID 40851490, 2025). "In addition to hypoglycaemia and reduced hepatic G6pc1 expression, hepatic glycogen stores, an additional source for hepatic glucose output, tended to be reduced in fasted Atp8b1 mutant mice compared to WT mice." (PMID 40851490, 2025).
inflammatory bowel disease (1 paper, 2024). A spectrum of small and large bowel inflammatory diseases of unknown etiology. "Therefore, here we investigated the role of ATP8B1 in the intestine in vivo and in vitro as well as in relation to inflammatory bowel disease [IBD]." (PMID 38366839, 2024). "Here we investigate the intestinal function of ATP8B1 in relation to inflammatory bowel diseases." (PMID 38366839, 2024).
lung diseases (1 paper, 2016). "Based on transcriptome profiling, our study indicates that Atp8b1 mutant mice may be susceptible to age-related lung diseases." (PMID 27689529, 2016).
metastatic tumors (1 paper, 2025). "Notably, significant genetic heterogeneity exists between primary and metastatic tumors, with mutations in ATP8B1 and SAMD9L prominently associated with metastasis." (PMID 41590495, 2025). "While most of our results align with existing studies, the unique identification of mutations such as SAMD9L and ATP8B1 in metastatic tumors and gender-specific enrichment of CDK8 and EPHB2 are less commonly reported and may represent new areas for investigation in personalized therapeutics." (PMID 41590495, 2025). "Similarly, distinct mutational patterns emerged between primary and metastatic tumors, with DMD and KMT2D more prevalent in primary tumors, while SAMD9L and ATP8B1 were found in metastases." (PMID 41590495, 2025). "ATP8B1 and SAMD9L mutations may mark metastatic disease, and gender-specific mutations suggest avenues for personalized therapy." (PMID 41590495, 2025).
Obesity (1 paper, 2022). Accumulation of substantial excess body fat. "P4-ATPase genes showed positive correlations with obesity markers, especially ATP8B1, which correlated with waist, hip, and BMI, and showed stronger correlations with obesity markers." (PMID 35807162, 2022). "The present study is the first study to analyse ATP8A1 and ATP8B1 in adipose tissue and to evaluate the effect of obesity and sex on their gene expression levels." (PMID 35807162, 2022). "The fact that a great variation in ATP8B1 expression could be explained by a positive effect of waist circumference instead of obesity per se reflects that VAT ATP8B1 is altered in visceral adipocyte expansion." (PMID 35807162, 2022). "In conclusion, our present study delineated the effects of obesity and sex on the gene expression of membrane phospholipid flippases, ATP8A1, and ATP8B1, in VAT." (PMID 35807162, 2022). "Our results showed a marked influence of obesity on VAT ATP8A1 and ATP8B1, although the effects of obesity were stronger in men for ATP8A1." (PMID 35807162, 2022). "Obesity increased ATP8A1 and ATP8B1 gene expression, although this effect was stronger in men than in women." (PMID 35807162, 2022). "An interesting finding is the presence of a significant interaction between obesity and sex in the expression of ATP8A1 and ATP8B1—namely, the stronger effect of obesity increasing the expression of these genes in men than in women." (PMID 35807162, 2022). "The present study aimed to analyse the effect of sex, obesity, and their interactions on the gene expression of two lipid flippases—ATP8A1 and ATP8B1—and their possible microRNA (miR) modulators in visceral adipose tissue (VAT)." (PMID 35807162, 2022). "The effects of obesity on ATP8A1 and ATP8B1 gene expression levels in VAT were sex-dependent, according to which higher effects were observed in men." (PMID 35807162, 2022). "Our results showed a marked influence of obesity on the expression of VAT ATP8A1 and ATP8B1, although the effects of obesity were stronger in men than in women, especially for ATP8B1." (PMID 35807162, 2022). "The present study aimed to study the effects of sex, obesity, and their interactions on the gene expression of two P4-ATPases—ATP8A1 and ATP8B1—and their possible miR modulators in VAT." (PMID 35807162, 2022). "Regression models supported a positive influence of obesity on the expression of ATP8A1 and ATP8B1." (PMID 35807162, 2022). "Obesity significantly increased the expression of ATP8A1 and ATP8B1 irrespective of sex." (PMID 35807162, 2022).
restless leg syndrome (1 paper, 2016). "However, two of these variants were associated with non-neurodevelopmental disorders: a BTBD9 variant linked to restless leg syndrome, and an ATP8B1 SNV associated with familial cholestasis, respectively." (PMID 27541642, 2016).
infection (29 papers, 2014 to 2025). The state of being infected such as from the introduction of a foreign agent such as serum, vaccine, antigenic substance or organism. "Mice bearing a missense mutant form of ATP8b1 present in many humans showed increased susceptibility to infection and infection–induced lung injury." (PMID 32493486, 2020).
cancer (7 papers, 2020 to 2023). A tumor composed of atypical neoplastic, often pleomorphic cells that invade other tissues. "ATP8B1 was initially identified as a driver gene for sporadic CRC by Genomic Identification of Significant Targets In Cancer (GISTIC)." (PMID 37686603, 2023). "Our important findings of the oncogenic role of ATP8B1 knockdown-driven metabolic disorder in LUSC carcinogenesis are likely applicable to other cancers." (PMID 35159102, 2022). "Furthermore, methylation patterns in SDMCs influenced the transcription of several genes (MEIS1, MIA3, PCDHAC2, SH3BP4, and ATP8B1) involved in well-known cancer-related pathways and cancer hallmarks (FDR < 0.05)." (PMID 36348462, 2022). "Homeostasis of membrane phospholipids also plays a pivotal role in cellular oncogenesis and cancer progression which emphasize that Atp8b1 may be a new therapeutic target in cancer, but the etiology and pathogenesis still need to be characterized." (PMID 36273194, 2022). "Our analysis suggests that ATP8B1 is a potential cancer suppressor in CRC patients and may offer new strategies for CRC therapy." (PMID 33062669, 2020).
tumor (5 papers, 2020 to 2025). "In order to further investigate the roles of CHKA in ATP8B1-related carcinogenesis and tumor progression, we then interfered with the CHKA gene via siRNAs in H520SH-ATP8B1 cells." (PMID 35159102, 2022). "Compared to the normal group, the expression of ATP8B1 was downregulated in the tumor group and the CRC cell lines, which declined with disease progression." (PMID 33062669, 2020). "The mechanism by which CHKA activation plays a tumor-promoting role in ATP8B1 knockdown cell lines remains unclear." (PMID 35159102, 2022).
genetic diseases (3 papers, 2022 to 2024). "Familial intrahepatic cholestasis 1 (FIC1) disease is a genetic disorder characterized by hepatic and gastrointestinal disease due to ATP8B1 deficiency, often requiring liver transplantation (LT)." (PMID 35626847, 2022). "Compensatory modified U1 snRNA is complementary to the mutated donor splicing site and exhibits great therapeutic potential as a new therapeutic strategy for ATP8B1 defects as well as other genetic diseases." (PMID 35783636, 2022).
metabolic disorder (2 papers, 2022). "In summary, we proposed ATP8B1 as a novel predictive biomarker in LUSC and targeting ATP8B1-driven specific metabolic disorder might be a promising therapeutic strategy for LUSC." (PMID 35159102, 2022). "We propose that targeting ATP8B1-driven specific metabolic disorder might be a promising therapeutic strategy for LUSC." (PMID 35159102, 2022). "Therefore, we proposed ATP8B1 as a novel predictive biomarker in LUSC and targeting ATP8B1-driven specific metabolic disorder might be a promising therapeutic strategy for LUSC." (PMID 35159102, 2022). "Therefore, for the first time, we propose ATP8B1 as a novel predictive biomarker in LUSC and targeting ATP8B1-driven specific metabolic disorder might be a promising therapeutic strategy for LUSC." (PMID 35159102, 2022).
autosomal dominant disease (1 paper, 2022). Autosomal dominant form of disease. "Cases from Korea and Japan with novel heterozygous mutations leading to BRIC1 were reported, showing that BRIC1, as an autosomal dominant disease, may also caused by ATP8B1 heterozygous mutations." (PMID 35783636, 2022).